SLC39A10 (solute carrier family 39 member 10)
Diseases named in the same sentence as SLC39A10 in open-access papers:
SLC39A10 is named in the same sentence as 42 diseases in open-access papers, as found by Europe PMC text mining. Sharing a sentence is not in itself a finding about the gene and the disease. The quoted sentences say what the papers report.
breast carcinoma (34 papers, 2011 to 2025). "For example, SLC39A10 (ZIP10) is overexpressed in gastric, hepatic, and breast cancers, where it enhances tumor growth and metastasis via Zn2+-dependent signaling pathways such as PI3K/AKT and MAPK/ERK." (PMID 40282424, 2025). "RP-7 downregulated prognostic markers (epidermal growth factor-like protein 8) and upregulated tumor suppressor genes (PLK2) in breast cancer cells, along with suppressing SLC39A10 involved in cancer progression." (PMID 38272230, 2024). "It has been reported that SLC39A10 promotes the metastasis of breast cancer and the malignant progression of gastric cancer by regulating the inflow of zinc." (PMID 39507258, 2024). "SLC39A10, an important member of the Zn2+ transporter family, has been reported to promote the malignant progression of breast cancer and early B-cell survival in the early stages of B-cell development." (PMID 37524874, 2023). "The high expression of SLC39A6 is a dependable marker for breast cancer (luminal A subtype), and elevated SLC39A10 mRNA levels were evident in the cancer cell lines of the highly aggressive breast cancer." (PMID 34925450, 2021). "High expression levels of SLC39A10 have been reported to be correlated with invasive behaviour by stimulating cell migration in breast cancer cells." (PMID 32875483, 2020).
Zinc deficiency (10 papers, 2011 to 2025). A deficiency of the essential metal Zinc; an essential cofactor for many enzymes. "Together, these findings indicate that SLC39A10 safeguards hematopoiesis by protecting against zinc deficiency‐induced necroptosis, thus providing compelling evidence that SLC39A10 and zinc homeostasis promote the development of fetal HSCs." (PMID 37068188, 2023). "With respect to the underlying mechanism, we found that zinc deficiency‐induced necroptosis contributes—at least in part—to the impaired properties of HSCs, implicating the SLC39A10‐zinc axis in the survival of fetal HSCs." (PMID 37068188, 2023). "Furthermore, it is shown that loss of Slc39a10 causes zinc deficiency in fetal HSCs, which in turn leads to DNA damage, apoptosis, and G1 cell cycle arrest." (PMID 37068188, 2023). "The results show that in zebrafish, Slc39a10 is a key regulator of the response to zinc deficiency." (PMID 37068188, 2023).
gastric cancer (6 papers, 2020 to 2025). A primary or metastatic malignant neoplasm involving the stomach. "In summary, a simple model is proposed to clarify the mechanism underlying the tumor-promoting role of SLC39A10 in gastric cancer." (PMID 37524874, 2023). "High expression of SLC39A10 was associated with worse prognosis of gastric cancer and glioblastoma." (PMID 32744318, 2020). "Functional studies showed that ectopic expression of SLC39A10 in gastric cancer cells dramatically enhanced the proliferation, colony formation, invasiveness abilities of these gastric cancer cells and tumorigenic potential in nude mice." (PMID 37524874, 2023). "The present study provided strong evidence to support the oncogenic role of SLC39A10 in gastric cancer." (PMID 37524874, 2023). "Taken together, our data demonstrate that SLC39A10 is a functional oncogene in gastric cancer and suggest that targeting CK2 is an alternative therapeutic strategy for gastric cancer patients with high SLC39A10 expression." (PMID 37524874, 2023). "As a result, the MAPK/ERK and PI3K/AKT pathways, two major downstream effectors of CK2, were activated, while c-Myc, a downstream target of these two pathways, formed a vicious feedback loop with SLC39A10 to drive the malignant progression of gastric cancer." (PMID 37524874, 2023). "In summary, we found that elevated expression of SLC39A10 is common in gastric cancers and is strongly related to poor patient outcomes." (PMID 37524874, 2023). "To fully comprehend how SLC39A10 performs its oncogenic function in gastric cancer cells, we first assessed its impact on intracellular Zn2+ homeostasis in two gastric cancer cell lines." (PMID 37524874, 2023). "We further investigated the impacts of SLC39A10 knockdown on the cell cycle distribution and apoptosis in gastric cancer cells." (PMID 37524874, 2023). "Further studies revealed that SLC39A10 exerts oncogenic roles in gastric cancer cells by elevating Zn2+ influx, thereby activating CK2 (casein kinase 2)-related signaling pathways." (PMID 37524874, 2023). "SLC39A10 increased the invasiveness of gastric cancer cells and their tumorigenic potential in mouse models." (PMID 37524874, 2023). "The results of functional studies showed that SLC39A10 knockdown strongly suppressed gastric cancer cell proliferation and colony formation in comparison with the control cells." (PMID 37524874, 2023). "We first demonstrated that SLC39A10 was frequently upregulated in gastric cancers in comparison with control subjects, and its expression was positively related to more aggressive phenotypes and poor patient survival." (PMID 37524874, 2023). "Briefly, elevated expression of SLC39A10 in gastric cancer cells promotes Zn2+ efflux, thereby increasing intracellular Zn2+ levels and promoting the formation of CK2β dimers, which in turn enhances the protein stability of CK2β and the holoenzyme activity of CK2." (PMID 37524874, 2023). "In addition, we clarified the mechanism of increased expression of SLC39A10 in gastric cancers by identifying SLC39A10 as a direct target of c-Myc using ChIP and dual-luciferase reporter assays." (PMID 37524874, 2023). "Conversely, SLC39A10 knockdown inhibited gastric cancer cell proliferation and colony formation." (PMID 37524874, 2023). "To determine the functions of SLC39A10 in gastric cancer cells, we first knocked down SLC39A10 in AGS and MKN45 cells using two different siRNAs (si- SLC39A10-#1 and -#3) specifically targeting SLC39A10 and verified their inhibition efficiency by qRT‒PCR and western blotting." (PMID 37524874, 2023). "Taken together, these data indicate that SLC39A10 is a potential target for gastric cancer therapy, and targeting CK2 may constitute an alternative therapeutic strategy for gastric cancer patients with high SLC39A10 expression." (PMID 37524874, 2023). "In addition, we demonstrated that SLC39A10 forms a vicious feedback loop with c-Myc to promote the malignant progression of gastric cancer." (PMID 37524874, 2023).
gastric cancer (continued). "In addition, c-Myc in turn upregulates the expression of SLC39A10 at the transcriptional level by directly binding to its promoter, forming a vicious loop promoting the malignant progression of gastric cancer." (PMID 37524874, 2023). "In addition, a series of functional studies in gastric cancer cells demonstrated that SLC39A10 promoted cell growth in vitro and in vivo, enhanced cell migration and invasion and induced cell cycle arrest and apoptosis." (PMID 37524874, 2023). "SLC39A10, a downstream target of c-Myc, in turn, also upregulated c-Myc expression, thereby forming a vicious feedback loop to promote the malignant progression of gastric cancer, implying that inhibition of c-Myc may attenuate the tumor-promoting effect of SLC39A10." (PMID 37524874, 2023). "To determine the therapeutic potential of SLC39A10 inhibition in gastric cancer, we stably knocked down SLC39A10 in MKN45 cells via a lentivirus system and used SLC39A10-knockdown MKN45 cells and control cells to establish a xenograft tumor model." (PMID 37524874, 2023). "Higher expression of SLC39A1, 5–7, and 9 indicated better OS, FPS, and PPS, and increased SLC39A2–4, 8, and SLC39A10 expression indicated poor OS, FP, and PPS in the patients with gastric cancer." (PMID 34925450, 2021). "Indeed, our data demonstrated that SLC39A10 overexpression and knockdown led to a significant increase and decrease in CK2 activity in gastric cancer cells, respectively, and that this effect was effectively reversed by the Zn2+ chelator TPEN or CX-4945." (PMID 37524874, 2023). "In support of these observations, our data showed that SLC39A10 overexpression significantly increased the phosphorylation of ERK and the phosphorylation of AKT at Ser473 and Ser129 but only slightly increased the phosphorylation of AKT at Thr308 in gastric cancer cells." (PMID 37524874, 2023). "However, the specific role of SLC39A10 in human cancers, including gastric cancer, has not been completely delineated." (PMID 37524874, 2023).
lymph node metastasis (6 papers, 2014 to 2023). "For patients with positive lymph node metastasis, SLC39A2, SLC39A3, SLC39A7, SLC39A8, SLC39A12 and SLC39A13 high expression suggested a worse OS, but SLC39A10 high expression suggested a benefit OS." (PMID 32744318, 2020).
prostate carcinoma (4 papers, 2021 to 2024). A carcinoma that arises from epithelial cells of the prostate gland. "MCM3AP-AS1 expedites cell multiplication and invasion through modulating miR-543-3p/SLC39A10/PTEN axis in prostate cancer." (PMID 33942704, 2021). "Moreover, up-regulation of MCM3AP-AS1 in prostate cancer cells has been found to increase proliferation and invasive capacity through sponging miR-543-3p and influencing the SLC39A10/PTEN/Akt axis." (PMID 35790972, 2022). "In vivo experiments in xenograft models of prostate cancer has also shown that MCM3AP-AS1 silencing considerably reduces tumor volume, and decreases the ratio of Ki67-expressing cells and expression levels of SLC39A10 in lesions." (PMID 35790972, 2022).
colon cancer (3 papers, 2020 to 2021). "The TCGA results indicated that SPIB, KRT24, PHLPP2, PLP1, BEST4, CA7, and C11orf86 were all downregulated, while KRT80, SLC39A10, AJUBA, FOXQ1, and CLDN1 exhibited upregulated levels in colon cancer." (PMID 32633726, 2020).
gastric adenocarcinoma (2 papers, 2023 to 2025). "Here, we found that SLC39A10 is highly expressed in gastric adenocarcinomas and observed the association of its upregulation with poor patient outcomes." (PMID 37524874, 2023). "Here, we found that SLC39A10 expression was frequently increased in gastric adenocarcinomas and that SLC39A10 upregulation was strongly associated with poor patient outcomes; in addition, we identified SLC39A10 as a direct target of c-Myc." (PMID 37524874, 2023). "Next, we investigated the correlation of these differentially expressed genes with the prognosis of gastric adenocarcinoma patients using the TCGA database and found a significant relationship between elevated expression of only SLC39A10 and poor patient survival." (PMID 37524874, 2023). "In addition, we selected 20 pairs of gastric adenocarcinoma tissues, which were diagnosed by H&E staining, and the matched noncancerous tissues and examined SLC39A10 expression in these tissues by qRT‒PCR analysis and IHC staining." (PMID 37524874, 2023).
glioblastoma (2 papers, 2020 to 2021). The most malignant astrocytic tumor (WHO grade IV). "used bioinformatics to identify four survival-associated differentially expressed genes (OSMR, HOXC10, SCARA3, and SLC39A10) in glioblastomas and found that glioblastoma patients with abnormal HOXC10 expression had poor survival outcomes." (PMID 34113572, 2021).
lymphoma (2 papers, 2017 to 2020). A malignant (clonal) proliferation of B- lymphocytes or T- lymphocytes which involves the lymph nodes, bone marrow and/or extranodal sites. "Our findings that high expression of SLC39A10 was associated with worse OS in patients with lymphoma-positive BC, but not correlated the OS in patients with lymphoma-negative BC suggested that SLC39A10 plays a vital role in metastatic BC." (PMID 32744318, 2020).
ovarian carcinoma (2 papers, 2021 to 2025). A malignant neoplasm originating from the surface ovarian epithelium. "We found downregulation of Gja4, a TZP key component, and Slc39a10, a zinc transporter, and the upregulation of Clu, a marker of apoptotic atretic follicles and ovarian cancer." (PMID 40693455, 2025).
pancreatic cancer (1 paper, 2025). "Among the identified transporters, SLC39A10 and SLC30A6 mediate PDAC-specific zinc metabolic reprogramming, SLC22B5 represents a novel finding in pancreatic cancer, and SLC55A2 is associated with mitochondrial dysfunction and aggressive tumor behavior." (PMID 40282424, 2025).
Parkinson disease (1 paper, 2025). A progressive degenerative disorder of the central nervous system characterized by loss of dopamine producing neurons in the substantia nigra and the presence of Lewy bodies in the substantia nigra and locus coeruleus. "In contrast, the Amyg showed upregulation of genes linked to oxidative phosphorylation (Atp6v1e1, Atp5mc2, Atp6v0e2), Parkinson disease (Snca, Calm1, Slc39a10), and regulation of actin cytoskeleton (Arpc3, Nckap1, Cfl1), indicating increased mitochondrial metabolism and structural plasticity." (PMID 41394722, 2025).
prostate adenocarcinoma (1 paper, 2025). "The volcano plot indicated significant upregulation of genes such as SIM2, HPN, and HOXC6 in prostate adenocarcinoma (PRAD), and significant downregulation of genes such as SLC39A2, SLC39A6, and SLC39A10." (PMID 40978029, 2025).
cancer (22 papers, 2011 to 2025). A tumor composed of atypical neoplastic, often pleomorphic cells that invade other tissues. "Then, four zinc transporter genes—ZIP4 (SLC39A4), ZIP6 (SLC39A6), ZIP7 (SLC39A7), and ZIP10 (SLC39A10)—were selected based on their documented roles in cancer-related signalling pathways, such as MAPK, PI3K/AKT, and epithelial-to-mesenchymal transition (EMT)." (PMID 40869403, 2025). "The results further confirmed the increased expression of SLC39A10 in cancer tissues compared with control tissues." (PMID 37524874, 2023). "Two close homologues within this family, ZIP6 (SLC39A6, also known as LIV-1) and ZIP10 (SLC39A10), with a 43.5% sequence identity, are on the same clade of the ZIP family phylogenetic tree and have both been independently implicated in cancer." (PMID 32797246, 2021). "Therefore, cancer cells may activate MTF1 in the presence of high concentrations of this metal, causing an underexpression of SLC39A10 and an overexpression of SLC30A1 in order to recover zinc homeostasis." (PMID 40176904, 2025). "Additionally, GSEA highlighted the significant connection of SLC39A10 and SLC30A6 to EMT and other cancer pathways, further supporting their potential as therapeutic targets in PDAC by influencing essential mechanisms of tumor progression." (PMID 40282424, 2025).
tumor (17 papers, 2020 to 2025). "Upregulation of SLC39A10 promoted tumor aggressiveness and was strongly associated with immune infiltration and poor patient outcomes in hepatocellular carcinoma." (PMID 37524874, 2023). "More specifically, the activation of NF-kB in tumor cells enhances the expression of several genes (including Ccl7, Cxcl1, Ccl5, Slc39a10, Lcn2, Zc3h12a, and Enpp2) that are implicated in tumor migration, angiogenesis, and formation of pre-metastatic niches." (PMID 33567747, 2021). "SLC39A10, another hub mRNA connected with the four exosomal hub miRNAs, encodes zinc transporter ZIP10 which is involved in cell migration during tumor progression." (PMID 33639954, 2021). "SLC39A10 which was down-regulated and positively associated with OS may act as a tumour suppressor gene in GBM." (PMID 32875483, 2020). "Therapeutically, this axis can be targeted, as exemplified by a novel STAT3 inhibitor, XYA-2, which co-suppresses MYC and SLC39A10 to elicit anti-tumor effects." (PMID 41583444, 2025). "In contrast, downregulated SLC39A10 likely acts as a tumor suppressor, as its elevated expression is correlated with improved patient survival." (PMID 41583444, 2025). "We also observed a positive correlation of SLC39A10 expression with tumor size, lymph node metastasis, and tumor stage using the TCGA database." (PMID 37524874, 2023). "The results showed that SLC39A10 knockdown significantly suppressed tumor growth and reduced tumor weight and the number of Ki-67‐positive cells compared with those in control animals." (PMID 37524874, 2023). "For five additional candidate targets including ITGA3 (n = 11), PCDH7 (n = 6), SLC39A10 (n = 6), ATP2B2 (n = 5), and HTR2B (n = 5), a quasi H − score ≥ 150 in at least 5 tumor types was also found." (PMID 33490264, 2021). "The results showed that xenograft tumors formed by SLC39A10-overexpressing MKN45 cells grew faster and exhibited a significant increase in tumor weight in comparison with the tumors formed by control cells, while CX-4945 treatment effectively reversed the effect of SLC39A10 overexpression." (PMID 37524874, 2023). "Furthermore, SLC39A10/ZIP10 has been demonstrated to be involved in physiological and pathological processes such as immunity and tumor formation." (PMID 37524874, 2023).
SLC39A10 also shares sentences with these, for which no sentence is quoted: osteosarcoma (7 papers); infection (3); neuroblastoma (3); hepatocellular carcinoma (2); lung carcinoma (2); neurologic disease (2); renal cell carcinoma (2); thyroid cancer (2); acrodermatitis enteropathica (1); acute myeloid leukaemia (1); age (1); anemia (1); diabetes (1); esophageal squamous cell carcinoma (1); follicular lymphoma (1); Hydrocephalus (1); Hyperglycemia (1); Immunodeficiency (1); inflammatory bowel disease (1); invasive breast carcinoma (1); leukemia (1); liver cancer (1); lymphoid leukemia (1); prion disease (1); renal carcinoma (1); triple-negative breast carcinoma (1); virus infection (1).